SOX2 (SRY-box transcription factor 2)
Diseases named in the same sentence as SOX2 in open-access papers (continued):
Sharing a sentence is not in itself a finding about the gene and the disease.
lung carcinoma (continued). "Furthermore, the 3D organoid population treated with SM-3 showed a marked reduction in the levels of stem cell markers (CD44 and CD133) and stem cell transcription factors (SOX2 and OCT4) in lung cancer organoids." (PMID 40287470, 2025). "In bronchial epithelial cells, PM2.5, diesel-exhausted particles PM2.5, and diesel-exhausted particles exposure silenced the miR-345-5p by the overexpression of lncRNA SOX2 overlapping transcript (SOX2-OT) and finally targeting the EGFR pathway in lung cancer development." (PMID 40248351, 2025). "Furthermore, it has been demonstrated that the CDK1/Sox2 axis acts as an important axis in the control and maintenance of the stemness of lung cancer cells, and inhibiting CDK1 increases the sensitivity of lung cancer to chemotherapeutics." (PMID 39820173, 2025). "In lung cancer cells, PAK5 interacts with Sox2 and phosphorylates Sox2." (PMID 36830998, 2023). "As SOX2 was positively modulated by its host gene SOX2OT in a cis-acting manner, we further investigated how SOX2OT interplays with GLI1 and functions in lung cancer stemness." (PMID 37149646, 2023). "We then analyzed the expression of the lung cancer lineage specifiers NKX2-1 and SOX2." (PMID 38093367, 2023). "In addition, CDK1 mRNA expression was negatively correlated with the overall survival of lung cancer patients, and CDK1/Sox2 regulated the activity of liver cancer stem cells in a positively regulated manner." (PMID 36339610, 2022). "SOX2 is a pleiotropic protooncogene related to stemness and EMT in lung cancer." (PMID 35719973, 2022). "CAFs also produce IGF2 that binds to the IGF1 receptor in lung cancer cells and activate the AKT/Sox2 pathway, leading to enhanced expression of P glycoprotein (PG-P), a member of the ATP-binding cassette transporters, that is capable of pumping out the chemotherapeutic drug." (PMID 33673405, 2021). "In lung cancer cell lines, down-regulation of NEAT1 could decrease the expression of stemness-related factors, including CD133, CD44, SOX2, OCT4 and NANOG." (PMID 33614649, 2021). "Interestingly, the data have shown several fold upregulation of DNA repair genes like RAD51b, RAD 18 and SOX2 cancer stem cell markers, MUC5AC and TGFBR2 in radiation resistant and caveolin-1, overexpressed A549 lung cancer cells." (PMID 34762666, 2021). "On the other hand, we did not observe TMPRSS4-, SLUG-, or TWIST1-mediated upregulation of SOX2, in lung cancer cells (data not shown), implying that TMPRSS4 contributes to CSC functions through various molecular mechanisms depending on the cellular context." (PMID 34809669, 2021). "Lung cancer cells expressing CD44 are enriched for stem‐like properties, and CD44‐positive cells show a higher level of expression for pluripotency markers (Oct‐4, Sox‐2) and increased resistance to cisplatin." (PMID 32991066, 2020).
lung carcinoma (continued). "However, TAMs also secrete MUC1 to enhance the expression of CSC-related and inflammatory genes in lung cancer cells, such as CD133, SOX2, and NF-κB, thus promoting the generation of lung cancer stem cells (LCSCs)." (PMID 33224886, 2020). "RT-qPCR and IHC staining assays here demonstrated that the expression levels of lung cancer markers and cancer stem cell features of lung cells, including Kras, c-Myc, ABCG2, OCT4, SOX2 and Aldh1a1, were markedly increased in lung tissues of PM2.5-challenged mice." (PMID 32554855, 2020). "Moreover, lung cancer stem cells express “stemness”-related biomarkers, such as CD44, CD24, CA133, CD13, CD90, ABCG2, SOX2, and EPCAM." (PMID 32849930, 2020). "The negative association between Sox2 and FOXA1 has been demonstrated in human breast and lung cancers, in which Sox2 represses FOXA1 gene expression." (PMID 33553286, 2020). "Notably, expression of USP4 was also significantly correlated with expression of Oct4 (R = 0.295; p < 0.001; n = 203) and Sox2 (R = 0.448; p < 0.001; n = 203), suggesting that USP4 is a potential positive regulator of lung cancer stemness." (PMID 32549341, 2020). "Knockdown of SOX2OT in lung cancer decreased EZH2 expression and inhibited cell proliferation by inducing G2/M arrest, while knockdown of SOX2OT decreased SOX2 and OCT4 expression and inhibited stem cell pluripotency and tumourigenesis in oesophageal squamous cell carcinoma." (PMID 32019566, 2020). "Furthermore, a comparison with the other two lung cancer subtypes revealed that, the TP63/SOX2/DMRT3 circuit was among the TFs up-regulated in a LUSC-specific manner, consistent with known properties of squamous lineage survival TFs." (PMID 29866045, 2018). "We also find that nicotine induces expression of Yap1 itself, and that the nicotine-mediated induction of Sox2 and Yap1 is not just specific to lung cancer cells but is also observed in human mesenchymal stem cells." (PMID 30322398, 2018). "On the other hand, we have shown NFATc1 inhibition does not result in SOX2 suppression, indicating NFATc2 is likely to be preferentially involved in lung cancers." (PMID 28737489, 2017). "In agreement, we showed that the treatment of pterostilbene dose-dependently suppressed the percentage of CD133+ lung cancer cells in the presence of TAMs and that this effect was mediated by the concomitant downregulation of MUC1, NF-κB, β-catenin, Sox2, and CD133." (PMID 27276704, 2016). "Stem cell transcription factors Oct4 and/or Sox2 have been found to bind to the P1 promoter region of the CD133 gene and ectopic Oct4 or Sox2 expression has been shown to trigger the CD133P1 activity in the lung cancer cell lines." (PMID 26992212, 2016). "Overexpression of both SOX2OT and SOX2 has been reported in human primary lung cancer tissues, in comparison with the corresponding non-tumor samples." (PMID 26136768, 2015). "Interestingly, the top 5 most highly expressed SAE-enriched transcription factors all have previously been established as having a role in airway biology and/or lung cancer, including FOXJ1, ELF3, TRIM29, SOX2, and FOXA1." (PMID 22375630, 2012).
lung carcinoma (continued). "These tumors stained positive for SPC (negative for CC10 and Sox2) and were morphologically similar to those produced in a lung cancer model in which adenoviral Cre was used to induce KrasG12D expression." (PMID 23285300, 2012). "The expression level of SOX2 antibody and MAGE antibody in squamous cell carcinoma was significantly higher than that in adenocarcinoma, and the expression level of SOX2 antibody in stage III lung cancer was significantly higher than that in stage I lung cancer." (PMID 38800369, 2024). "The findings of this study indicate that SOX2 may be a key player in the dedifferentiation of lung cancer cells, as demonstrated by the higher levels of upregulated SOX2 expression seen in dedifferentiated CSCs derived from non-CSCs." (PMID 39547513, 2024). "EBC2 lung cancer cells transfected with ATF/SOX2 failed to grow tumors in nude mice." (PMID 38612911, 2024). "In the literature, we could not find any study demonstrating SOX-2 levels in the DEN-induced lung cancer model." (PMID 37259369, 2023). "Thus, our clinical data further confirmed that LKB1 loss increased the DNA methylation and expression level of ALKBH5, which resulting in the demethylation of m6A modification on SOX2, SMAD7, and MYC, and maintaining their expression for KRAS mutant lung cancer." (PMID 34016959, 2021). "However, the exact role of SOX2 in mediating SCLC progression of in lung cancer patients has not been fully elucidated due to the limited accessibility of patient tissues for research purposes." (PMID 32130794, 2020). "Nevertheless, chelerythrine chloride was able to inhibit the growth of lung cancer cell lines from different proximal/distal origins, the β-catenin nuclear localization in several lung histologies, and β-catenin and perhaps SOX2 and MYC expression regardless of the tissue origin." (PMID 31935827, 2020). "Furthermore, in the context of lung cancer the subtype of KRAS-induced tumors (i.e., adenocarcinoma vs squamous carcinoma) is regulated by activation of the NOTCH signaling pathway and expression of SOX2." (PMID 31399087, 2019). "Therefore we hypothesized that ZNF322A in lung cancer may contribute to lung cancer stem cell-like (CSC-like) reprogramming through transcriptionally regulating stemness transcription factors, such as Oct4, Nanog, Sox2 and c-Myc." (PMID 30258097, 2019). "In sum, our results thus far have demonstrated that CSCs expand in lung cancer tumoroids and tumors wherein the Wnt signaling pathway plays a crucial role in lung CSC development and this signaling involves several important known targets such as Sox2, ALDH, and Nos2." (PMID 31796785, 2019). "Furthermore, studies in lung cancer, as well as head and neck squamous cell carcinoma, have shown that stable downregulation of SOX2 via shRNAs decreases ABCG2, which implicates this transporter in SOX2-related drug resistance." (PMID 28388544, 2017). "We showed that the expression of SOX2 is upregulated more in dedifferentiated CSCs/CICs derived from non-CSCs/CICs than in non-CSCs/CICs, indicating that SOX2 might be a responsible key molecule in the dedifferentiation of lung cancer cells." (PMID 27418136, 2016). "Although previous studies suggested the efficacy of SOR against lung cancer to the best of our knowledge, there is no study evaluating the relationship between JNK and COX-2 signaling and SOX-2 in the lung premalignant microenvironment." (PMID 37259369, 2023). "The expression levels of CD44, SOX2, Nanog, Oct4, and ABCG2 in lung cancer nodules from Tumor + CIH groups were significantly upregulated compared with the lung cancer tissues from Tumor + Nor mice." (PMID 33596919, 2021).
lung carcinoma (continued). "For lung cancer, squamous cell carcinomas frequently revealed no immune reactivity for CK7 or CK20 but are positive for CK5/6, p63, SOX2 and p40." (PMID 30315187, 2018). "Consistent with our findings, it has also been shown by others that overexpression of ALDH1A1 rather than other isoforms (ALDH1A3 and ALDH3A1) increased lung cancer cell transformation and CSC phenotype by activating stem cell drivers Nanog, Oct4, and Sox2." (PMID 28415606, 2017). "In this study, we applied RT-PCR to examine the differential expression of Bmi1, CD133, CD44, Sox2, Nanog, OCT4 and Msi2 mRNA in bronchoscopic biopsy specimens from lung cancer and non-cancer patients." (PMID 23683495, 2013). "LUSC tumors frequently amplify the SOX2 locus, whereas LUAD tumors do not, indicating that different mechanisms are involved in genome dysregulation in these two subtypes of lung cancer." (PMID 37738673, 2023). "In a recent study oflung cancers with wild-type EGFR, the activation of EGFR upregulated SOX2, therebydecreasing apoptosis through BCL2L1, a phenomenon that was notably absent inEGFR-mutant lung cancers.A similar pathway was reported in a prostate cancer cell line, also with wild-typeEGFR." (PMID 25686219, 2015). "However, the positive expression rates of CD133, CD44, Sox2, OCT4 and Msi2 did not correlate with age, gender, histological type, stage and differentiation of lung cancer." (PMID 23683495, 2013).
prostate carcinoma (177 papers, 2011 to 2026). A carcinoma that arises from epithelial cells of the prostate gland. "SOX2 is integral to the advancement of prostate cancer, and its functional disorder has been linked to a variety of other malignancies." (PMID 39976818, 2025). "This manuscript will analyze the structure and physiological functions of SOX2 in the context of prostate cancer, while concurrently investigating the associated signaling pathways." (PMID 39976818, 2025). "The up-regulation of SOX2 in prostate cancer is associated with lineage plasticity, defined as the tumor's ability to transition between distinct developmental pathways." (PMID 39976818, 2025). "Elevated SOX2 levels have been detected in prostate cancer tissues and are associated with higher tumor grade, aggressive phenotype, and poor prognosis." (PMID 40821114, 2025). "The increased levels of SOX2 in androgen-independent prostate cancer are likely linked to its functions in maintaining stem cell-like properties, promoting cellular growth, and influencing cell migration." (PMID 39976818, 2025). "TWIST1 upregulation of SOX2 was associated with the promotion of cancer stem cell-like properties in prostate cancer cells and also with the progression of triple-negative breast cancer." (PMID 39593172, 2024). "Another recent study demonstrated that the co-culturing of prostate cancer cells with primary cancer associated fibroblasts (CAFs) induced over a 20-fold increase in the expression level of SOX2 in cancer cells." (PMID 37371076, 2023). "On the basis of these findings, we determined the protein expression of the top markers associated with EMT (CD44, ALDH1, Oct-4, TGFB, Nanog, and Sox2) using immunoblotting in all prostate cancer cell lines." (PMID 37476073, 2023). "The CTP stemness phenotype was confirmed by the spheroids detected in CTP-DB and -BL cultures in addition to the high expression of nestin, Nanog, and SOX2, which are shown to be linked to prostate cancer development, progression, invasion, and metastasis." (PMID 37894361, 2023). "SOX2 expression in the primary tumor is significantly associated with lymph node metastasis and highly aggressive neuroendocrine differentiation of prostate cancer." (PMID 34809669, 2021). "The tumors developed in mice resembled the neuroendocrine variant of prostate cancer, expressing increased levels of epigenetic regulators SOX2 and EZH2." (PMID 31366128, 2019). "Our results demonstrate that SOX2/OCT4-associated CSCs play a critical role in the therapeutic resistance of prostate cancer to taxane chemotherapy." (PMID 31500347, 2019). "Sox2 promotes cell proliferation and inhibits apoptosis in prostate cancer and is associated with the severity of disease." (PMID 29369542, 2018). "MiR-34b-3p regulates the expression of stem cell-related factors, including c-Myc, Sox2, Met and Notch1, which have also been implicated in prostate cancer." (PMID 26107383, 2015). "In previous studies, the expression of stemness markers, including Sox2 has been observed in prostate cancer, and linked to disease progression and unfavorable outcome." (PMID 26107383, 2015).